MDK (midkine)
Diseases named in the same sentence as MDK in open-access papers (continued):
Sharing a sentence is not in itself a finding about the gene and the disease.
tumor (continued). "Through ST technology, we localized tumor-derived MDK and its stromal receptor NCL, and observed their co-enrichment at the tumor–stroma interface, suggesting spatial coordination of this signaling pathway with immune suppression." (PMID 41249133, 2025). "Western blot analysis further confirmed that protein expression levels of MDK and NCL were significantly upregulated in tumor samples compared to controls." (PMID 40396179, 2025). "When MDK expression was restored, the inhibitory effect of ACT001 on tumours was comparable to that of the wild type." (PMID 40468625, 2025). "After knocking down MDK, the inhibitory effect of ACT001 on the tumour was decreased compared with the WT group (p < .05), but ACT001 still had an inhibitory effect." (PMID 40468625, 2025). "Consistent with this, we found that MDK–NCL activity negatively correlated with ImmuneScore and StromalScore—as validated in the TCGA database—implying its role in suppressing anti-tumor immunity." (PMID 41249133, 2025). "Subsequently, we examined the ligand-receptor pairs of these signals, noting that ligands such as MIF, MDK, and APP are highly expressed on C0 RPS4Y1+ tumor cells and are instrumental in mediating communication with other tumor microenvironments." (PMID 40230840, 2025). "Our findings reveal that the MDK-NCL pathway contributes to immunosuppression and tumor immune evasion mechanisms, providing novel insights into the potential of targeting this axis as a therapeutic strategy." (PMID 41246334, 2025). "This would therefore suggest that MDK may be a promising target for limiting the metastatic spread of cancers, by simultaneously limiting the acquisition of mesenchymal phenotypes, migratory ability, and access to the lymphatic vasculature important for tumor spread." (PMID 40429950, 2025). "On the one hand, tumor cell C1_EGFR+ and C2_STAT1+ directly act on CD8T_GNLY+ through the MDK–(ITGA4+ITGB1) axis and the MIF–(CD74+CXCR4) axis to promote tumor proliferation." (PMID 40948762, 2025). "Key pathways involved include MDK, PTN, SPP1, and FN1, all of which play central roles in immune regulation and tumor progression." (PMID 40837013, 2025). "The cross-sample consistency supports the conclusion that High_FAM49B_EP drives the differentiation of CXCL3_TAMs into SPP1_TAMs via the MDK-NCL signaling pathway, thereby contributing to the remodeling of the immunosuppressive tumor microenvironment." (PMID 41246334, 2025). "In cancers, though, MDK seems to exert a primarily inhibitory effect on CD8+ T cells, as there is evidence that MDK can be secreted by tumor cells to suppress the antitumor activity of CD8+ T cells." (PMID 40429950, 2025). "Spatial transcriptomics revealed that MDK-NCL signaling activity was markedly elevated at the tumor-immune interface, a region characterized by high cellular density and active immune-tumor interactions." (PMID 40396179, 2025). "This analysis suggests an important role of MDK and PTN signaling in tumor proliferation in Group 3 and Group 4 MBs, presenting a potential drug target." (PMID 39659836, 2024). "Metastatic tumor cells clustered with adrenergic cells and showed high expression of adrenergic signature genes PHOX2B, MDK, and KCNQ2." (PMID 38358826, 2024). "In contrast, compared to normal tissues, tumor tissues showed noticeably elevated expression levels of SAA1, MDK, and ISG15." (PMID 39440053, 2024). "The expression of secreted protein‐coding genes, including MDK, HGF, RARRES2, GDF15, IL6 and MIA, was concentrated in the tumour cell‐enriched region, thus confirming the expression specificity of these signalling molecules." (PMID 38318640, 2024). "An increase in MDK results in an interaction with its receptor LRP1, which is expressed by tumour-infiltrating macrophages and promotes immunosuppressive macrophage polarization." (PMID 38896142, 2024).
tumor (continued). "Intriguingly, expression of MDK and POSTN increased with time in biopsies from tumor 4, correlating with the switch from therapeutic response to resistance formation in this patient." (PMID 38942020, 2024). "Consistent with the results of single‐cell data, MDK signalling, HGF signalling, chemerin signalling, and GDF15 signalling were also observed to be hyperactive signals primarily sent by the tumour cells based on the ST data." (PMID 38318640, 2024). "The mRNA expression levels of STMN1, CLSPN, MDK, RNFT2, PRR11, and RNF157 were significantly increased in HCC tumor tissue; on the contrary, GHR was significantly decreased compared with normal tissues." (PMID 37542549, 2023). "Further, our results identified potential ligand-receptor pairs (MDK/LRP1, MDK/ALK, GAS6/MERTK, and GAS6/AXL) for cell communication between these two types of cells and tumor cells." (PMID 37733241, 2023). "Here, MDK not only recruits peripheral immune cells, but also activates CD8+ T cells, establishing a neuro-immune-cancer axis that promotes tumor growth." (PMID 38098484, 2023). "Ligand–receptor pairs, such as PROS1-AXL, NAMPT-INSR, MDK-LRP1, MDK-ALK, GAS6-MERTK, and GAS6-AXL, between endothelial and tumor cells exhibited a higher communication possibility than that between endothelial cells and thyrocytes." (PMID 37733241, 2023). "Expectedly, with the progression of ESCC, the expression of MDK and NCL in tumour tissue increased step by step, and the close location indicated the interaction between CAFs and tumour." (PMID 36855810, 2023). "In particular, the interaction between Midkine (MDK, secreted by tumor cells) and a number of MDK-receptors (ITGA4, ITGA6, ITGB1, NCL, LRP1) on CD8+ T cells appears to be a recurrent immunosuppressive pathway seen across all three patients." (PMID 36973261, 2023). "The MDK and GAS signaling pathway has been confirmed to regulate several biological processes in cells, including proliferation, survival and migration in tumor microenvironment by binding to their receptors." (PMID 37733241, 2023). "Sorafenib treatment enhances MDK expression, stimulating the accumulation of immunosuppressive myeloid-derived suppressor cells (MDSC) in the tumor microenvironment, further secreting IL-10." (PMID 37240085, 2023). "In contrast, ID3 + cells highly expressed genes such as MDK, ZEB1, and LGR5 that play important roles in tumor stemness." (PMID 35347134, 2022). "Here, we elucidate the molecular mechanism by which MDK modulates tumor progression, including the suppression of AMPK signaling, to provide more clues to advance the clinical application of MDK in cancer diagnosis and prognosis." (PMID 35487917, 2022). "MDK can combine with its receptor LRP1, which is beneficial to tumor-infiltrating macrophages, promoting myeloid inhibitory cell differentiation (MDSCs)." (PMID 35935940, 2022). "Of the overlapping set of proteins, the levels of WFDC2, S100P, CD55, MDK, THBS2, and MFAP2 were more than 2-fold higher in PDAC compared with tumor-adjacent tissue in our data." (PMID 36923555, 2022). "The results above illustrate a dual role of BO‐110 repressing prolymphangiogenic factors both at the tumor and at the LEC level (via MDK and VEGFR3, respectively)." (PMID 34762341, 2021). "MDK and PTN interact with a plethora of surface receptors to initiate tumor promoting cell motility/invasion, survival, and drug resistance." (PMID 34502484, 2021). "Midkine (MDK) is a 13-kDA small heparin-binding growth factor detected in the majority of HCC tissues and rarely expressed in surrounding non-tumor tissues." (PMID 33562077, 2021). "Overexpression of MDK, CENPM, and SSR2 promotes tumor metastasis, angiogenesis, and tumorigenesis, leading to poor prognosis in patients with HCC." (PMID 34900444, 2021).
tumor (continued). "To identify the tumor cells and non-tumor lung cells, we first mapped the expression of six genes (FOLR1, AGR3, and SFTPD for normal hung lung cells, and EPCAM, MDK, and SOX4 for cancer cells) to each cluster to identify the cell types in our study." (PMID 32549766, 2020). "The basal tumor cluster #3 demonstrated transcriptional downregulation of HRAS; cell dormancy; and a higher expression of IGFBP7, MDK, and B2M, recapitulating those of the tipifarnib-resistant (or cluster B) BC159-T#3 PDX tumor cells." (PMID 32460812, 2020). "The tumor cells in cluster B showed similar characteristics to those of tipifarnib-resistant tumor cells, including downregulation of the RAS and MAPK signaling pathways and upregulation of IGFBP7, MDK, and B2M mRNA." (PMID 32460812, 2020). "Our work also demonstrates that the pharmacological targeting of the MDK/ALK axis efficiently acts on the population of GICs in vitro and in tumor xenografts." (PMID 32308772, 2020). "Antagonizing MDK significantly reduced GBM cell survival (p < 0.5 and <0.001 for NCI131 and NCI827, respectively) and tumor sphere formation (p < 0.001)." (PMID 31811117, 2019). "Consistent with the data from the RNAseq analysis, three HER2 fusion genes—ZNF207 (exon 1–2)/HER2 (exon 18–30), MDK (exon 1–4)/HER2 (exon 11–30), and NOS2 (exon 1–2)/HER2 (exon 2–30)—were further confirmed in these tumor DNA samples." (PMID 25889497, 2015). "Eight of these immune response genes (SPP1, PDPN, IL1RN, IL6, CCL8, MDK, IRF7, and HRH4) were expressed between 1.25–1.59 fold higher in the microglia/macrophage enriched population compared to bulk tumor." (PMID 22937035, 2012). "Supporting the thesis on midkine involvement in early colon carcinogenesis and its possible downregulation in advanced cancers, we found a negative correlation between midkine concentration and tumor size but did not observed any other association with the disease advancement." (PMID 22562257, 2012). "The involvement of both MDK and AGR2 in oncogenesis and tumor progression has been previously reported." (PMID 20525245, 2010). "Conversely, midkine (MDK) staining was found across all patients and localized to the cytoplasm of the ASPS tumor cells themselves." (PMID 19146682, 2009). "Subsequent analysis utilizing the CellPhoneDB-secreted ligand‒receptor database revealed that tumor cells with high PSMD1 expression predominantly employ ligands such as MIF, MDK, and SPP1 as signaling molecules to communicate with immune cells within the microenvironment." (PMID 41535254, 2026). "We hypothesize that the high EFFscore subgroup may secrete ANGPTL4 and MDK to activate myCAF populations, particularly LRRC15+ Fib and STRA6+ Fib, thereby driving late-stage ECM remodeling and promoting tumor invasion and metastasis." (PMID 41383622, 2025). "However, along with the tumor grade, the prevalence of ENST00000395566 increased, while the diversity of MDK isoforms gradually decreased, as assessed by the Shannon diversity index." (PMID 40835683, 2025). "The communication network diagram of the MDK - NCL ligand - receptor provides the specific communication pattern and potential regulatory mechanism between cells, providing clues for understanding the information transfer between tumor cells and other cells." (PMID 40636123, 2025). "MDK seems to be involved in tumor cell communication through binding several of its receptors, including syndecan 1 (SDC1), SDC4, NCL, and LRP1, and MDK from tumors seems to bind to NCL on macrophages and lymphocytes, though the functional consequences have not been explored." (PMID 40429950, 2025). "ST evidently highlighted that MDK was highly expressed predominantly in epithelial and ciliated cells and that the MDK-NCL interaction occurs in specific tissue regions, contributing to immune suppression and tumour progression." (PMID 41312167, 2025).
tumor (continued). "The combination of chemotherapy and immunotherapy, such as PD-1/PD-L1 therapy or MDK-NCL signaling suppression therapy, may effectively inhibit tumor progression and hold significant promise for HGSOC treatments." (PMID 40725006, 2025). "Tumor clusters 2, 3, and 5 lacked receptors of tumor progression ligand-receptor MDK - SDC4 and exhibited lower expression of the receptors of MDK - NCL." (PMID 40036264, 2025). "In addition, epithelial cells specifically interacted with mCAFs through the LAMININ, COLLAGEN, FN1, and MDK pathways, suggesting that in the tumor group, epithelial cells may promote cell proliferation and migration by attracting and recruiting mCAFs into the tumor microenvironment." (PMID 41187171, 2025). "Our study did not directly examine the role of the MDK-NCL interaction in tumor proliferation but only focused specifically on NCL, which has been infrequently studied in this context." (PMID 40036264, 2025). "MDK expression was comparable in the tumor samples and respective primary cell cultures, suggesting that malignant cells are the predominant MDK source in GBM tumor microenvironment (TME)." (PMID 40835683, 2025). "Patients with high MDK-NCL expression groups exhibit increased infiltration of regulatory T cells (Tregs), myeloid-derived suppressor cells (MDSCs), and M2-like macrophages, which are known to promote immune evasion and tumor progression." (PMID 40396179, 2025). "Furthermore, MDK is known to activate Notch2 signaling in cancer cells, leading to epithelial-mesenchymal transition (EMT), drug resistance, and aggressive tumor behavior." (PMID 40500394, 2025). "This suggests that MDK-NCL signaling may downregulate antigen presentation, reducing tumor immunogenicity." (PMID 40396179, 2025). "Our results indicate that MDK-NCL plays a pivotal role in the interaction between malignant, immune, and stromal cells, particularly by fostering an immunosuppressive environment that supports tumor immune evasion." (PMID 40396179, 2025). "Furthermore, MDK suppression in SBC5R and SBC3R cells using shMDK impaired tumor cell proliferation." (PMID 40620228, 2025). "Midkine (MDK) engages extracellular−matrix receptors to foster an immunosuppressive, pro−angiogenic niche, while the MIF–CD74 pathway dampens innate immunity to facilitate tumor progression." (PMID 40948762, 2025). "We previously demonstrated that murine Nf1-OPG growth is tightly regulated by neuron-immune-tumor interactions, such that Nf1-mutant neurons, specifically retinal ganglion cells (RGCs), induce T cell-TAM stromal support through the expression of midkine (Mdk), a secreted growth factor." (PMID 41497446, 2025). "Moreover, patients with high MDK-NCL expression exhibited poorer survival outcomes, underscoring the pathway’s role in tumor progression and immune evasion." (PMID 40396179, 2025). "Collectively, these spatial findings support our hypothesis that necroptosis may activate the MDK–NCL signaling axis via DAMP release, which in turn could mediate the establishment of an immunosuppressive microenvironment conducive to tumor metastasis." (PMID 41249133, 2025). "Similarly, MDK and PTN, members of the heparin-binding growth factor family, are extensively involved in tumor cell proliferation, EMT, angiogenesis, and immune suppression." (PMID 41383622, 2025). "Thus, distinct cell types within a tumor can apparently act as a source for POSTN and MDK, raising the question about the identity of their effector cells." (PMID 38942020, 2024). "Additionally, MDK-SDC2 and MDK-(ITGA4+ITGB1) signals from fibroblasts and tumor cells were only received by CPVLhi TAMs." (PMID 39776914, 2024). "Cell proliferation assay demonstrated significant differences between CAFs with or without tumour supernatant/knockdown of NCL/MDK inhibitor, underlining the importance of MDK–NCL pathway in early ESCC microenvironment." (PMID 36855810, 2023).
tumor (continued). "The MDK/LRP1, MDK/ALK, GAS6/MERTK, and GAS6/AXL were identified as potential ligand-receptor pairs involved in the interactions between fibroblasts/endothelial cells and tumor cells." (PMID 37733241, 2023). "Next, the results of cell-cell communication analysis suggested that pericytes interact with broad immune cells via MDK-NCL pathways in metastasis samples, MIF-(CD74+CXCR4) and MIF-(CD74+CC44) interaction especially occurred between different cell types in tumor and normal samples." (PMID 37335089, 2023). "Collectively, we could also conclude that Schwann cells promote PDAC progression in vivo by shaping the phenotypes of tumor cells and CAF, which was induced by MDK and IL-1, respectively." (PMID 37524695, 2023). "MDK/ALK/ALP and GAS/MERTK/AXL interactions between tumor cells and endothelial cells/fibroblasts may be potential therapeutic targets for PTC." (PMID 37733241, 2023). "Finally, interactome analyses between pre-metastatic tumor cells and CD8 + T-lymphocytes uncover a putative role for the Midkine pathway in immune-modulation and this is confirmed by scRNAseq of tumors from humanized mice." (PMID 36973261, 2023). "MDK regulates EMT, which plays a significant role in the migration of tumor cells in NSCLC." (PMID 37240085, 2023). "A promising human MDK blockade system has already been established in vitro using prostate cancer xenografts, where synthetic siRNA in combination with the chemotherapeutic paclitaxel (PTX) affects tumor cell proliferation, apoptosis, and angiogenesis." (PMID 38098484, 2023). "In addition, FNDC4 was negatively correlated with AFP, a tumor marker of HCC, and other cancer-related genes such as AHSA1, GDF1, GPC3 and MDK." (PMID 38021165, 2023). "Notably, MDK/LRP1, MDK/ALK, GAS6/MERTK, and GAS6/AXL between fibroblasts and tumor cells exhibited a higher communication possibility than that between fibroblasts and thyrocytes." (PMID 37733241, 2023). "For example, MDK (ligand) and NCL (receptor) were highly expressed in the tumor microenvironment (TME) of recurrent samples, consistent with previous studies implicating the roles of this ligand–receptor pair in tumorigenesis and the MK-deficiency-reduced tissue infiltration of microglia." (PMID 35844565, 2022). "In contrast, MDK-overexpressing MHCC97H cells accelerated tumor growth and tumor weight in vivo." (PMID 35487917, 2022). "Differential gene expression analysis by Seurat34,35 identified 160 genes uniquely upregulated in tumor cells compared with TAF and normal kidney, including genes previously reported (e.g., GPNMB8, SQSTM1/p6236, MMP237, PTGDS38) and genes involved in tumor metastasis (e.g. MMP11, MDK, DCN, PDPN)." (PMID 36028490, 2022). "The result demonstrated that MDK was most frequently related to cancer, while the LKB1-AMPK axis was usually considered to be an important tumor suppressor indicating that cancer would be an appropriate system to elucidate the biological function of MDK and LKB1-AMPK." (PMID 35487917, 2022). "We also validated the expression of MDK by IHC staining using 5 normal skin samples, 10 samples with AK, and 16 patients with primary tumors and single or multiple recurrences of cSCC, comprising matched ANS and tumor samples." (PMID 36438481, 2022). "Note that for SK‐Mel‐147, the immunoadsorption assay detects the human form of MDK (i.e., not from the host), thus allowing to monitor tumor‐driven effects of this protein." (PMID 34762341, 2021). "Collectively, the data above illustrate how the Vegfr3Luc MetAlert mice can be geared to the discovery of antilymphangiogenic factors, BO‐110 in this case, with novel modes of action in tumor cells and HLEC, with an IFN‐dependent inhibition of MDK and VEGFR3, respectively." (PMID 34762341, 2021).